CYP2E1 (cytochrome P450 family 2 subfamily E member 1)
Diseases named in the same sentence as CYP2E1 in open-access papers (continued):
Sharing a sentence is not in itself a finding about the gene and the disease.
endotoxemia (5 papers, 2017 to 2024). "The effects of intestinal CYP2E1 on gut barrier dysfunction and endotoxemia are worsened with concomitant LPS administration." (PMID 38214802, 2024). "Intestinal CYP2E1-mediated oxidative stress can also sensitize the liver to toxicity through endotoxemia and gut-derived TNF-α through the CYP2E1-thioredoxin-ASK1-JNK1 pathway." (PMID 38214802, 2024). "CYP2E1-mediated ROS can also stimulate endotoxemia and elevate serum levels of LPS, which can travel to the liver, upregulating pro-inflammatory mediators, including tumor necrosis factor-alpha (TNF-α) and hypoxia-inducible factor 1-alpha (HIF1-α)." (PMID 38247468, 2023). "Alterations of ALDH2, CYP2E1, and iNOS can also contribute to intestinal permeability and endotoxemia in the progression of ALD." (PMID 38247468, 2023). "Upregulated intestinal CYP2E1 increases nitroxidative stress and promotes gut leakage, which may lead to inflammatory liver damage and endotoxemia." (PMID 36557739, 2022). "CYP2E1-mediated oxidative stress can also sensitize the liver to toxicity via endotoxemia and intestinal TNF-α via a CYP2E1-thioredoxin-ASK1-JNK1 pathway." (PMID 38247468, 2023). "In addition, this study showed that intestinal and hepatic CYP2E1, induced by binge alcohol exposure, plays an important role in promoting oxidative stress, gut leakiness, and endotoxemia, all of which could be blunted by a physiologically relevant dose of antioxidant EA." (PMID 34573017, 2021).
esophageal cancer (5 papers, 2007 to 2022). A primary or metastatic malignant neoplasm involving the esophagus. "Similarly, Yang and colleagues assessed the influence of the CYP2E1 c2 variant allele on the risk of esophageal cancer in conjunction with alcohol consumption in 165 diagnosed Japanese subjects and 495 randomly selected controls." (PMID 29342885, 2018). "Additionally, one study evaluating the identical association among black South-African males showed an increased risk of oesophageal cancer among drinkers carrying the CYP2E1*5A or *6 alleles." (PMID 17996038, 2007). "The aim of this study was to explore the cytochrome P450 2E1 (CYP2E1) RsaI/PstI polymorphism and risk of esophageal cancer (EC) in mainland Chinese populations." (PMID 23226753, 2012).
head and neck cancer (5 papers, 2010 to 2020). A primary or metastatic malignant neoplasm affecting the head and neck. "The study results showed that the OR for individuals carrying one mutation allele (CYP2E1*5 -1293C) and having a head and neck cancer was 1.11 compared to individuals with the homozygous wild-type CYP2E1*5 -1293G allele." (PMID 25299224, 2014). "While a G-1293C mutation at the 5′ promoter region of CYP2E1 will alter the gene's expression, the impact of this SNP on an individual's risk for developing head and neck cancer remains controversial." (PMID 25299224, 2014). "Another meta-analysis of case-control studies on the association between CYP2E1 polymorphisms and head and neck cancer risk showed that individuals, especially Asians, homozygous for CYP2E1*5 -1293C had an increased risk for developing head and neck cancer." (PMID 25299224, 2014). "Genetic polymorphisms in CYP2E1 have been linked to altered susceptibility to liver injury, head and neck cancer and other carcinomas in some epidemiological studies." (PMID 22606226, 2012). "In the present meta-analysis, we examined the association between two widely studied CYP2E1 polymorphisms (PstI/RsaI, DraI) and head and neck cancer risk." (PMID 20969746, 2010). "Our meta-analysis gave an overall OR of 1.96 (95% CI: 1.33-2.90, P < 0.001, PQ = 0.87) for head and neck cancer risk among c2 homozygotes of CYP2E1 RsaI/PstI polymorphism compared with the wild type." (PMID 20969746, 2010). "Recent meta-analyses suggest that CYP2E1 PstI/RsaI and DraI polymorphisms may affect susceptibility to many cancers such as lung cancer and head and neck cancer." (PMID 22606226, 2012). "Our results indicate that the CYP2E1-PstI/RsaI and DraI polymorphisms may be a risk factor for head and neck cancer in Asian populations, and particularly for individual homozygotes for the unfavourable gene variant." (PMID 20969746, 2010). "CYP2E1, which is a major component of the microsomal system involved in the metabolism of ethanol and acetone among phase I enzymes, has been widely studied as a cause of susceptibility to head and neck cancer." (PMID 20969746, 2010). "We performed a meta-analysis using 21 eligible case-control studies with a total of 4,951 patients and 6,071 controls to summarize the data on the association between the CYP2E1 PstI/RsaI and DraI polymorphism and head and neck cancer risk, especially by interacting with smoking or alcohol." (PMID 20969746, 2010). "A meta-analysis including 12562 cases was performed to examine the association between the CYP2E1 Rsa I/Pst I RFLP and susceptibility to head and neck cancers." (PMID 25299224, 2014).
leukemia (5 papers, 2012 to 2023). A malignant (clonal) hematologic disorder, involving hematopoietic stem cells and characterized by the presence of primitive or atypical myeloid or lymphoid cells in the bone marrow and the blood. "Thus, it is reasonable to hypothesize that elevated CYP2E1 activity and/or decreased activity of NQO1 predisposes individuals exposed to xenobiotics to a greater risk of leukemia." (PMID 23066397, 2012). "Although the role of CYP2E1 expression in the pathogenesis of AML remains unclear, polymorphisms in these gene have been shown to be associated with the risk of leukemia but not the risk of treatment-related leukemia." (PMID 32373530, 2020).
malnutrition (5 papers, 2007 to 2023). Inadequate nutrition resulting from poor diet, malabsorption, or abnormal nutrient distribution. "Conditions which can increase NAPQI production, such as induction of CYP2E1 by alcohol, or conditions that decrease GSH stores, such as malnutrition, are postulated to increase the risk of acetaminophen-induced hepatic injury." (PMID 17537264, 2007). "In protein-calorie malnutrition, both GSH and CYP2E1 quantities would be reduced (as detailed by a reduction in both GSH and CYP2E1 messenger RNA) and thus there would be no net overall effect on toxicity." (PMID 29067481, 2018).
melanoma (5 papers, 2020 to 2023). A malignant, usually aggressive tumor composed of atypical, neoplastic melanocytes. "Moreover, CYP2E1 was shown to be further downregulated in metastatic melanoma compared to primary melanoma in two of three datasets (left)." (PMID 36831600, 2023). "Ability of melanoma cells to metabolize dacarbazine was determined by expressional analysis of CYP1A1, CYP1A2, CYP2E1 followed by CYP1A1 protein level evaluation by the ELISA method." (PMID 36533319, 2023). "When compared to normal skin tissues, primary melanoma tissues showed reduced ADH1B, CYP2E1, and CAT gene expression in at least two of three datasets (left), consistent with previous observations for ADH1B." (PMID 36831600, 2023). "The present study determined the mRNA levels of the cytochromes CYP1A1, CYP1A2 and CYP2E1, as well as the protein levels of cytochrome CYP1A1 in melanoma cells." (PMID 36533319, 2023).
schizophrenia (5 papers, 2012 to 2024). A major psychotic disorder characterized by abnormalities in the perception or expression of reality. "False‐positive report probability values for the association between NOTCH4 rs2071287, NOTCH4 rs204993, and CYP2E1 rs2070673 and the risk of schizophrenia." (PMID 39698532, 2024). "This study provides the first evidence of DNA methylation levels in the promoter of CYP2E1 gene associated with schizophrenia and TD." (PMID 36494682, 2022). "To investigate the association of the polymorphisms in the CYP2E1 gene with schizophrenia, we detected allele and genotype frequencies of 10 SNPs in the promoter of CYP2E1 and 5′-VNTR in 228 schizophrenic patients and 384 healthy controls." (PMID 22606226, 2012). "We investigated the possible association of CYP2E1 polymorphisms with susceptibility to schizophrenia in the Chinese Han Population as well as the relationship with response to risperidone in schizophrenia patients." (PMID 22606226, 2012). "Our study has, for the first time, provided evidence for an association pattern of CYP2E1 polymorphisms with schizophrenia in a Chinese Han population." (PMID 22606226, 2012). "In a case-control study, we identified 11 polymorphisms in the 5' flanking region of CYP2E1 in 228 schizophrenia patients and 384 healthy controls of Chinese Han origin." (PMID 22606226, 2012). "In conclusion, the case-control study revealed that CYP2E1 polymorphisms were associated with susceptibility to schizophrenia in the Chinese Han population." (PMID 22606226, 2012). "Our two-part study investigated the contribution of polymorphisms in the CYP2E1 gene to both schizophrenia susceptibility and therapeutic response to risperidone in a Chinese Han population-based association analysis." (PMID 22606226, 2012). "We found statistically significant association for SNP rs8192766 and rs2070673 of the CYP2E1 gene with schizophrenia." (PMID 22606226, 2012). "Our results suggest that CYP2E1 may be a potential risk gene for schizophrenia in the Chinese Han population." (PMID 22606226, 2012). "In addition, further accumulation of data on the role of the CYP2E1 polymorphisms in the pathogenesis of schizophrenia and cellular or protein expression experiments should be conducted." (PMID 22606226, 2012). "Association analysis of 11 markers in the CYP2E1 gene among schizophrenia patients and controls." (PMID 22606226, 2012). "Consequently, the purpose of this study was to examine: 1) the association between the CYP2E1 gene polymorphisms and schizophrenia, 2) the relationship between CYP2E1 gene polymorphisms and the clinical efficacy of risperidone treatment in schizophrenia patients." (PMID 22606226, 2012). "CYP2E1 is considered as an oxidative stress-related gene, however, no study has been reported on the DNA methylation levels of the CYP2E1 in schizophrenia or TD." (PMID 36494682, 2022). "Accordingly, we suspected that subjects with certain polymorphisms and haplotypes of CYP2E1 might have an increased ability to activate endogenous or exogenous toxins, leading to increased oxidative stress in the brain and, therefore, an increased relative risk of schizophrenia." (PMID 22606226, 2012). "On the other hand, low CYP2E1 activity might protect individuals from schizophrenia because of the lower production of metabolites of ROS." (PMID 22606226, 2012). "We therefore considered that CYP2E1 might be involved in the onset or etiology of schizophrenia." (PMID 22606226, 2012). "However, data from our study may provide a basis for future investigations on the role which CYP2E1 plays in the etiology of schizophrenia and risperidone treatment outcome." (PMID 22606226, 2012). "However, rs2515641 in CYP2E1 was found to be significantly related to nonresponse to RIS treatment for schizophrenia in a Chinese cohort (p = 0.007)." (PMID 38375040, 2024).
type 1 diabetes (5 papers, 2005 to 2022). "Previous studies have found increased expression with type 1 diabetes of Cyp2e1 in lymphocytes and heart and Cp in corpus cavernosum, whereas Lox undergoes reduced expression in cavernosum." (PMID 19915678, 2009). "In addition, CYP2E1 activates the liver damage in stress-induced type 1 diabetes (T1D) liver damage." (PMID 34204038, 2021). "Moreover, gene expression levels of human CYP2E1 were related to cytotoxicity and DNA damage by nitrosamines in pancreatic beta-cell lines, suggesting that such gene environment interactions are also relevant in type 1 diabetes." (PMID 16263519, 2005).
acute myeloid leukemia (4 papers, 2012 to 2024). Acute myeloid leukemia (AML) is a group of neoplasms arising from precursor cells committed to the myeloid cell-line differentiation. "The CYP2E1*5 allele is linked to an increased risk of developing acute myeloid leukemia and acute lymphoblastic leukemia." (PMID 37047003, 2023). "Through the conversion of a range of xenobiotics into hazardous intermediates such as reactive oxygen species and free radicals, CYP2E1 contributes to an elevated acute myeloid leukemia risk." (PMID 37047003, 2023). "Therefore, this review suggests that CYP2E1 and its mutations can be a therapeutic or diagnostic target in acute myeloid leukemia." (PMID 37047003, 2023). "CYP2E1 -1293G>A/-1053C>T polymorphisms are associated to increased risk of developing acute myeloid leukemia (AML) and acute lymphocytic leukemia (ALL)." (PMID 30154939, 2018). "The CYP2E1*5 allele is associated with a higher risk of de novo acute myeloid leukemia (AML) and acute lymphoblastic leukemia." (PMID 23066397, 2012). "This research has the potential to give insight into novel strategies for the treatment of acute myeloid leukemia via CYP2E1." (PMID 37047003, 2023). "Recent research has shown a sustained interest in determining the regulators of CYP2E1 expression and activity as an emerging field that requires further investigation in acute myeloid leukemia evolution." (PMID 37047003, 2023). "The purpose of this review was to describe the pathophysiology of acute myeloid leukemia as well as the role of CYP2E1 in the xenobiotic metabolism that governs the myeloid leukemia microenvironment." (PMID 37047003, 2023). "The CYP2E1*5B(C-1019T) polymorphism has not been linked to therapy-related acute myeloid leukemia or myelodysplastic syndrome." (PMID 37047003, 2023). "Recent research has shown a sustained interest in determining the regulators of cytochrome P450, family 2, subfamily E, member 1 (CYP2E1) expression and activity as an emerging field that requires further investigation in acute myeloid leukemia evolution." (PMID 37047003, 2023).
bladder cancer (4 papers, 2010 to 2018). "As such, it is hard to make definitive conclusions about the clinical value of CYP2E1 gene variants and bladder cancer." (PMID 30278485, 2018). "Our results revealed that, on the whole, significant associations between CYP2E1 gene polymorphisms and bladder cancer were found in all genetic models." (PMID 30278485, 2018). "Our results illustrated that there are significant associations between CYP2E1 gene polymorphisms and bladder cancer in all genetic models (P < .05)." (PMID 30278485, 2018). "Subgroup study showed that there were also significant associations between CYP2E1 gene polymorphisms and bladder cancer in Asian people (P < .05)." (PMID 30278485, 2018). "Meta-analysis revealed that there were significant associations between CYP2E1 gene polymorphisms and bladder cancer in all genetic models (P < .05)." (PMID 30278485, 2018). "A subgroup study showed that there are also significant associations between CYP2E1 gene polymorphisms and bladder cancer in Asian people." (PMID 30278485, 2018). "For the additive, dominant, recessive, codominant, and allele models, 1, 2, 2, 1, and 2 studies, respectively, reported a significant association between CYP2E1 gene polymorphisms and bladder cancer." (PMID 30278485, 2018). "Recent studies have investigated the association of CYP2E1 gene polymorphisms with bladder cancer risk but have shown contradictory results." (PMID 30278485, 2018). "In our study, 8 reports that studied the association of CYP2E1 gene polymorphisms with bladder cancer risk were analyzed." (PMID 30278485, 2018). "In summary, the results of this meta-analysis suggest that the current article adds to the evidence of an association between CYP2E1 gene polymorphisms and bladder cancer progression." (PMID 30278485, 2018). "The subgroup study showed that there are also significant associations between CYP2E1 gene polymorphisms and bladder cancer in Asian populations." (PMID 30278485, 2018). "The present study provides evidence for an association between CYP2E1 gene polymorphisms and bladder cancer progression, and suggests that CYP2E1 gene polymorphisms might be a protective factor against bladder cancer in Asian people." (PMID 30278485, 2018). "Hence, we performed a systematic literature review and meta-analysis to assess the association between CYP2E1 gene polymorphisms and bladder cancer." (PMID 30278485, 2018). "However, studies with larger sample sizes are needed to confirm the correlation between CYP2E1 gene polymorphisms and bladder cancer." (PMID 30278485, 2018). "However, studies with larger sample sizes are needed to definitively determine the correlation between CYP2E1 gene polymorphisms and bladder cancer." (PMID 30278485, 2018). "The potential molecular basis for the association between the CYP2E1 C1/C1 genotype and bladder cancer risk may be related to the expression levels of the gene." (PMID 30278485, 2018). "Systematic literature searches were conducted with PubMed, Excerpt Medica Database, Science Direct/Elsevier, China National Knowledge Infrastructure, and the Cochrane Library up to January 2018 for studies that involved the association of CYP2E1 gene polymorphisms with bladder cancer risk." (PMID 30278485, 2018). "The consistency of these findings with experimental observations of GSTT1, GSTZ1, and CYP2E1 activity strengthens the hypothesis that DBPs cause bladder cancer and suggests possible mechanisms as well as the classes of compounds likely to be implicated." (PMID 20675267, 2010). "Associations between THMs and bladder cancer were stronger among subjects who were GSTT1 +/+ or +/− versus GSTT1 null (pinteraction = 0.021), GSTZ1 rs1046428 CT/TT versus CC (pinteraction = 0.018), or CYP2E1 rs2031920 CC versus CT/TT (pinteraction = 0.035)." (PMID 20675267, 2010).
bladder cancer (continued). "In this study we investigated the combined influence of DBP exposure and polymorphisms in glutathione S-transferase (GSTT1, GSTZ1) and cytochrome P450 (CYP2E1) genes in the metabolic pathways of selected by-products on bladder cancer in a hospital-based case–control study in Spain." (PMID 20675267, 2010). "We estimated effects of THMs and GSTT1, GSTZ1, and CYP2E1 polymorphisms on bladder cancer using adjusted logistic regression models with and without interaction terms." (PMID 20675267, 2010). "We calculated the main effects for the respective SNPs within increasing quartile strata of long-term average THMs where we found increasing relative risks for bladder cancer for GSTT1 present, GSTZ1 rs1046428 CT/TT, and CYP2E1 rs2031920 CC." (PMID 20675267, 2010).
breast tumors (4 papers, 2013 to 2024). "Clinical studies have shown that CYP2E1 is highly expressed in breast tumors compared to normal breast tissue." (PMID 29362861, 2018). "Clinical studies have indicated that stage I breast tumours express higher CYP2E1 mRNA levels compared to stages II, III and IV." (PMID 24207099, 2013). "Clinical studies have indicated higher CYP2E1 gene expression in breast tumours than normal tissues and decreasing CYP2E1 levels as carcinogenesis progresses suggesting that this enzyme might serve important functions in breast carcinogenesis." (PMID 24207099, 2013).
chronic hepatitis C (4 papers, 2004 to 2018). "CYP2E1 antibodies have been pathogenically associated with chronic hepatitis C (CHC)." (PMID 30305319, 2018). "CYP2E1 IgG has been detected in patients with chronic hepatitis C (CHC)." (PMID 30305319, 2018). "Indeed, a correlation of CYP2E1 expression in liver biopsies from chronic hepatitis C carriers with liver inflammation and fibrosis score was reported, although contradictory data also exist." (PMID 26035647, 2015). "In chronic hepatitis C (CHC), CYP2E1 autoantibodies are a biomarker for necroinflammation, which may suggest functional roles for these autoantibodies." (PMID 30305319, 2018).